AATK (apoptosis associated tyrosine kinase)
Diseases named in the same sentence as AATK in open-access papers (continued):
Sharing a sentence is not in itself a finding about the gene and the disease.
sarcoma (1 paper, 2022). A usually aggressive malignant neoplasm of the soft tissue or bone. "The promoter methylation of the AATK promoter was analyzed via CoBRA in various cancer cell lines from head and neck, breast, thyroid, sarcoma, ovary, lung, brain, and bone marrow." (PMID 35902728, 2022).
serous ovarian neoplasms (1 paper, 2014). "Methylation of AATK has been reported in low grade serous ovarian neoplasms." (PMID 25352953, 2014).
small cell lung carcinoma (1 paper, 2014). Small cell lung cancer (SCLC) is a highly aggressive malignant neoplasm, accounting for 10-15% of lung cancer cases, characterized byrapid growth, and early metastasis. "In small cell lung cancer AATK was hypermethylated in four out of 12 tissues (data not shown)." (PMID 25352953, 2014).
T-cell lymphoma (1 paper, 2021). "Finally, in primary NHL, AATK/miR-1250 methylation was frequently detected in both B- and T-cell NHL, hence implicated in lymphomagenesis." (PMID 34044822, 2021). "Moreover, unlike miR-124-1 and miR-129-2, which were preferentially methylated in B-cell rather than T-cell NHL, AATK/miR-1250 methylation was comparable between B-cell and T-cell NHL." (PMID 34044822, 2021).
tumor (10 papers, 2014 to 2025). "Here we identified the apoptosis associated tyrosine kinase (AATK) as an epigenetically downregulated tumor related gene." (PMID 25352953, 2014). "miR-1250-5p is a novel tumor suppressive intronic miRNA co-regulated and silenced by promoter DNA methylation of its host gene AATK in NHL." (PMID 34044822, 2021). "As a CpG island is present at the promoter of miR-1250 host gene AATK, we postulated that miR-1250-5p is a tumor suppressor miRNA silenced by promoter DNA methylation of its host gene AATK in NHL." (PMID 34044822, 2021). "Our data showed that 83% (73/88) of patients expressed a low level of AATK protein in tumor tissues, and that the differences in patient outcome were significant (p < 0.05) in terms of overall patient survival between the two groups." (PMID 32552862, 2020). "To verify the ability of AATK to suppress tumor growth as do other tumor suppressor genes, we performed colony formation and proliferation assays in human cancer cell lines." (PMID 25352953, 2014). "In summary, hypermethylation of AATK was also demonstrated in primary tumor tissues of cancer patients." (PMID 25352953, 2014). "To functionally test AATK and its ability to suppress tumor formation, we performed colony formation and proliferation assays." (PMID 25352953, 2014). "Thus, we further analyzed the methylation of two 450 K array probes (cg15665342 and cg26717786) within the CGI of AATK in 711 normal tissues and 8893 tumor samples from the TCGA project." (PMID 35902728, 2022). "In addition, the expression of AATK and the corresponding methylation at these CpGs significantly correlates in these tumor samples." (PMID 35902728, 2022). "Taken together, these data indicated that methylation of AATK/miR-1250 was tumor-specific in NHL." (PMID 34044822, 2021). "This miRNA is an intronic miRNA within the AATK gene that is also downregulated in tumor." (PMID 30913346, 2019). "However, the functional mechanism underlying the tumor suppressive function of AATK in respect to its kinase activity has not been analyzed in detail." (PMID 35902728, 2022). "Notably, 42% of the 142 methylation‐regulated tumour genes are controlled by multiple methylation sites, especially MGMT (14 sites), AATK (12 sites), VRK2, and FGFR2 (10 sites)." (PMID 41292185, 2025).
cancer (9 papers, 2014 to 2025). A tumor composed of atypical neoplastic, often pleomorphic cells that invade other tissues. "We further find the cell cycle drivers cyclin D1 (CCND1) and WEE1 to be repressed by AATK induction and identify the loss of AATK via epigenetic silencing as correlated to impaired overall patient survival in various cancers." (PMID 35902728, 2022). "By analyzing PDA subtypes in The Cancer Genome Atlas, we identified that epigenetic silencing of apoptosis-associated tyrosine kinase (AATK) inversely was correlated with mRNA expression and was enriched in the quasi-mesenchymal cancer subtype." (PMID 32552862, 2020). "In our study, we have identified the apoptosis associated tyrosine kinase (AATK) gene as a novel epigenetically inactivated target gene in human cancer." (PMID 25352953, 2014). "Silencing of the Apoptosis associated Tyrosine Kinase gene (AATK) has been described in cancer." (PMID 35902728, 2022). "Thus, it will be interesting to evaluate whether aberrant AATK methylation may represent a novel biomarker for prognostic or diagnostic purposes in human cancer." (PMID 25352953, 2014). "AATK, a tumor suppressor gene frequently hypermethylated in cancer, has shown promise for therapeutic reactivation to improve outcomes." (PMID 40227503, 2025). "Strikingly, AATK expression is epigenetically regulated in cancer cell lines and reduced expression of AATK is a common molecular phenotype in carcinogenesis associated to poor disease outcome." (PMID 35902728, 2022). "Although we show that AATK is epigenetically downregulated in various cancers, further mechanisms of downregulation have been described." (PMID 35902728, 2022). "Categories “Cell cycle” (6 out of 7 data sets), “Apoptosis” (5/7), and “Cancer gene census” (4/7) were also correlated with reduced AATK expression." (PMID 35902728, 2022). "Aberrant epigenetic silencing of AATK contributes to proliferation in cells in invasive cancer lesions in vivo in KPC mice." (PMID 32552862, 2020). "In cancer cells, we observed an epigenetic silencing of the AATK CpG island promoter, which was reversed by Aza treatment as shown by AATK re-expression and promoter demethylation." (PMID 25352953, 2014). "Since in general both alleles of a tumor suppressor gene are inactivated, these findings indicate that deletion and epigenetic inactivation are two important pathways for the inactivation of AATK in human cancer." (PMID 25352953, 2014). "We analyzed the epigenetic regulation of AATK in several human cancer cell lines and normal tissues by methylation and expression analysis." (PMID 25352953, 2014). "Methylation was reversed by 5-aza-2′-deoxycytidine treatment leading to re-expression of AATK in cancer cell lines." (PMID 25352953, 2014). "It will be fascinating to investigate the functional relationship of AATK epigenetic inactivation in cancer cell lines and their inability to differentiate or to undergo apoptosis." (PMID 25352953, 2014). "Aberrant methylation of AATK was also revealed in primary lung (40%) and breast (53%) cancers, but was found to be significantly less methylated in matching normal breast tissues (17%; p<0.01)." (PMID 25352953, 2014). "This suggests that downregulation of AATK in cancer cell lines is due to its promoter hypermethylation." (PMID 25352953, 2014). "The CGI of AATK was methylated in 10 out of 14, i.e., 71% of the analyzed cancer cell lines." (PMID 35902728, 2022). "Furthermore, expression of AATK was correlated with a better patient survival for different cancer entities." (PMID 35902728, 2022). "In the present work, we analyzed the function and regulation of AATK in several cancer entities." (PMID 35902728, 2022). "We also observed that the AATK gene is the target of miR‐182‐5p that is upregulated in cancer." (PMID 30913346, 2019). "Demethylation of AATK is accompanied by re-expression of AATK in cancer cell lines." (PMID 25352953, 2014).
cancer (continued). "Hypermethylation of AATK occurred frequently in 13 out of 14 (93%) human cancer cell lines." (PMID 25352953, 2014). "Consistent with this, AATK protein expression significantly associates with nuclear VAV1 localization in PDA patients, in which AATK-negative cases were overrepresented with cytosolic VAV1 localization, epithelial-to-mesenchymal transition, and dissemination of cancer cells." (PMID 32552862, 2020). "Conversely, cancer cells in those mice with low or negative AATK expression, cytosolic VAV1 localization was enriched." (PMID 32552862, 2020). "To clarify whether CTCF could regulate AATK expression, we transfected CTCF in HeLa, A549 and H322 cancer cells." (PMID 25352953, 2014). "However, the expression of AATK and its functional role in the course of PDA initiation, progression, and clinical outcome have not been determined in large clinical cohorts, despite its potential apoptosis-promoting role in other cancers." (PMID 32552862, 2020).
AATK also shares sentences with these, for which no sentence is quoted: cervix cancer (2 papers); adenocarcinoma (1); Alzheimer disease (1); Anxiety (1); anxiety disorder (1); asthma (1); attention deficit hyperactive disorder (1); autism (1); centronuclear myopathy (1); cerebral malaria (1); colon adenocarcinoma (1); colon cancer (1); colon polyps (1); depression (1); developmental delay (1); frontotemporal dementia (1); Hepatomegaly (1); hereditary spastic paraplegia (1); infection (1); Intellectual disability (1); larynx cancer (1); leiomyosarcoma (1); leukemia (1); lung squamous cell carcinoma (1); malignant glioma (1); metastatic melanoma (1); multiple myeloma (1); neck cancer (1); neurological disorders (1); pancreas carcinoma (1).
A further 6 diseases each share a sentence with AATK in 1 paper.